CD4 (CD4 molecule)
Diseases named in the same sentence as CD4 in open-access papers (continued):
Sharing a sentence is not in itself a finding about the gene and the disease.
infection (continued). "Regarding the opposite trends of these two T-cells, an interrelationship has been suggested, with CD4+ regulatory T-cells producing IL-10 to promote memory CD8+ T-cell maturation during infection regression." (PMID 36039499, 2022). "Despite a significantly greater reduction in plasma VL in the vaccinated macaques, the vaccine was unable to control the initial destruction of intestinal CD4+ T cells in VI RMs in the short 12 wks post infection follow-up period." (PMID 36560823, 2022). "The latent reservoir is largely composed of memory CD4+ T cells and persists, in part, due to clonal expansion of cells harboring intact provirus and continued infection by low levels of virus, despite effective ART." (PMID 36345941, 2022). "In contrast, other subsets of memory CD4 T cells, along with naïve CD4 T cells, appear refractory to productive infection and die as bystander cells." (PMID 35784348, 2022). "CD39+ virus-specific CD4+ T-cells increased during infection, peaked at day 88 after the onset of symptoms (63.2%) for the index patient and day 25 (41.38%) for the reference patient, and continuously decreased afterward." (PMID 35746736, 2022). "At day 5 after infection, we performed CD4 and p24 immunostaining and quantified their expression by flow cytometry." (PMID 35133986, 2022). "Since IL-10 is involved in lessening the effector CD4+ T cell responses, increased pre-infection levels of this cytokine can potentially downregulate immune responses responsible for combating HIV." (PMID 35165387, 2022). "Both natural infection and vaccines produce long-term memory T cells, CD4+ and CD78+, which would protect the population particularly by avoiding severe infections and being associated with a better prognosis." (PMID 35833134, 2022). "During infection with M. tuberculosis, inflammatory monocytes were necessary for CD4+ T-cell priming because they transported bacteria to the dLN." (PMID 35585969, 2022). "Consideration of the genetic identity of both the Dengue and Zika flaviviruses as well as the cross-reactivity of relevant T cells along with the actions of CD4+ cytotoxic cells in these infections are also presented." (PMID 36159640, 2022). "At 8 and 14 weeks post-infection, animal 72-15 had 325 and 203 CD4+ T cells/μL, respectively; and 72-17 had a frequency 15% and 22% CD4+ of CD3+ T cells, respectively." (PMID 36561749, 2022). "The human immunodeficiency virus (HIV) infects primarily memory CD4 + T cells, leading to a diminished capacity of the immune system to defend against otherwise relatively harmless infections." (PMID 34743182, 2022). "The reduced presence of regulatory CD4+ T cells (Treg) found in infected dogs would also optimize T-cell activation and effector functions during infection, as these Treg cells can suppress the antiparasitic CD4+ T-cell response." (PMID 35746555, 2022). "A recent study in Nigeria found that in those with HCV/HBV/HIV triple-infection, CD4+ counts are significantly lower as compared to those with HIV infection alone." (PMID 35082320, 2022). "To quantify the effect of IFN-α on cell-free and cell-to-cell infection, we adopted this experimental method: in the static cultures of Jurkat cells, an HIV-1-susceptible human CD4+ T cell line, HIV-1 executes both cell-free and cell-to-cell infection." (PMID 35468127, 2022). "Contrary to total CD4+ cells, which drop sharply in the infection, memory CD4+ cells are effectively formed in COVID‐19 patients and readily stimulated in vitro." (PMID 35837843, 2022). "Clinicians should maintain a high index of suspicion for MAC osteomyelitis when preliminary cultures are unrevealing and infection is refractory to treatment, despite adequate CD4 counts and appropriate ART therapy." (PMID 36381873, 2022).
infection (continued). "For example, studies have demonstrated that adoptively transferred naïve or effector CD4+ T cells differentiate into Th1 cells, migrate to the site of infection and release high levels of IFN-γ, a cytokine with key roles in clearing intracellular infections." (PMID 35880171, 2022). "POU2F1 is a required transcription factor for T-cell response to infection and the development of CD4+ memory T-cells." (PMID 36225796, 2022). "These functional subsets likely contributed to protection and survival in the immunized mice because elimination of CD4 T cells prior to infection resulted in increased viral load and reduced survival." (PMID 35260804, 2022). "We applied LC-DIAMS to identify HLA-A*02:01–restricted epitopes presented on CD4+ T cells that had been infected in vitro with a GFP-tagged HIV-1 that is capable of a single-round infection (hereafter referred to as ΔEnv-NL4.3-EGFP)." (PMID 35394875, 2022). "S727P had been seen in an earlier study of SIVmac239ΔGY infection in RM and was shown to increase infection in gut CD4+ T cells during acute infection." (PMID 35714165, 2022). "IL3000-infected mice had increased numbers of extravascular B cells in the brain parenchyma (two-way ANOVA, p-value = 0.0341), whereas in the 1/148 infection, T helper cells (CD4+) were increased by twofold (two-way ANOVA, p-value = 0.0.0305)." (PMID 35787830, 2022). "In individuals suffering from HIV, Tfh are the CD4+ T cell population with the highest rate of infection in vivo, and the single cell type most capable of supporting HIV infection in vitro." (PMID 35493515, 2022). "Many clinical trials have shown that intracellular ATP levels in CD4+ T cells can act as markers for identifying infection or allograft rejection." (PMID 36313425, 2022). "As a result, the DNA synthesis during infection of activated CD4+ T-cells occurs within 12–16 h, whereas it takes up to 36 h during macrophage infection." (PMID 35893688, 2022). "Ongoing studies examining CD4+ T cell responses at the site of infection and the contribution of other cell types that produce IFNγ should further our mechanistic understanding of vaccine-mediated protection." (PMID 36248898, 2022). "The number of CD4+ T cells in the spleen significantly (p ≤ 0.0332) increased in B.m and B.m+B16 groups relative to naive and B16 groups during the entire infection period." (PMID 35814662, 2022). "Next, concatenated CD4+ T cells or only IL-4eGFP+CD4+ T cells were splitted based on organ and time after infection." (PMID 35950748, 2022). "The presence of SARS‐CoV‐2‐reactive CD4 T cells is an indication of protective immunity from re‐infection or severe course of infection." (PMID 35396852, 2022). "CTLA‐4+CD4+ T cells expressing high CD25 levels were also increased in symptomatic infection, but conventional CD45RA− memory CD4+ T cells became important sources of CTLA‐4 expression during asymptomatic infection compared to symptomatic counterparts." (PMID 35475529, 2022). "Pinpointing memory CD4+ T cells among the multiple helper subsets generated in response to infection has been a challenge." (PMID 35858332, 2022). "This is especially important during an active infection, where the signals produced by the infected cells modulate the differentiation of CD4+ T cells, and these cells activate or inhibit other cells of the immune system." (PMID 36678366, 2022). "The latent reservoir is formed early upon infection in both CD4-positive (CD4+) T lymphocytes and myeloid cells, but resting memory CD4+ T cells harbor the majority of proviral DNA (3, –, 6)." (PMID 35499323, 2022). "Throughout the course of the infection, CD4+ and CD8+ T cell concentrations in the peripheral blood (Figures E3A and E3B) and BAL (Figures E3C and E3D) were not different between the two infection groups." (PMID 35412961, 2022).
infection (continued). "In summary, these data show the remarkable induction of CD4+ T cells with cytolytic potential during infection with T. cruzi, an effector subpopulation whose appearance in the spleen parallels and largely outnumbers that of classic GzB- IFN-γ+ Th1 cells." (PMID 35670567, 2022). "Our data strongly suggest that CTL responses correlate with protection against PRRSV-1 transplacental infection, being executed by CD4 T cells (IFN-γ related) and/or CD4/CD8α DN T cells (TNF-α related)." (PMID 36798517, 2022). "We chose to initially apply our immunometabolic model of CD4+ T cell differentiation on a time course study of resolving CDI given the clinical relevance of C. difficile as well as the importance of host CD4+ T cell responses during and after infection." (PMID 36418318, 2022). "After infection, interleukin-12 (IL-12) is expressed by antigen-presenting cells (APCs) and promotes the differentiation of antigen-specific CD4+ T cells into IFN-γ and TNF-producing Th1 cells, which activate macrophages to kill internalized parasites." (PMID 36290364, 2022). "In turn, the percentage of CD4+CD8α+ double positive T cell subpopulations in the spleen of turkeys was significantly affected by infection, and it was higher in birds challenged with C. perfringens than in those administered LPS (P = 0.032)." (PMID 35883183, 2022). "Shown are CD4 T cells of all organs after infection (days 6, 8, and 10 post Nb infection) concatenated into one UMAP and splitted by organ (upper row)." (PMID 35950748, 2022). "We next compared the overall infection and latency establishment under IL-2 or IL-15 stimulation for all the CD4+ T cells subsets." (PMID 35499323, 2022). "While augmented TNT formation in DCs promoted productive infection, as was previously observed, a significant reduction in productive infection was observed in DC/CD4+ T-cell co-cultures, indicating antiviral activity in this setting." (PMID 35204813, 2022). "Taken together, these data reveal that HIV-1 induces dramatic reprogramming during infection of resting memory CD4+ T cells driven largely by Vpr." (PMID 35417711, 2022). "The depletion of MGL2+ cells conferred mice with partial resistance to the infection and abrogated the increase of CD4+/CD25+ FoxP3+ Tregs induced by the infection." (PMID 36271272, 2022). "Upon challenge infection with P. berghei, higher levels of CD4+ T cell and memory B cell responses in the spleen were also found in VLPs-immunized mice compared to non-immunized control." (PMID 35214662, 2022). "This study also provided the detection of IFN-γ-producing memory CD4+ T cells in the rGP19-immunized mice later infected with E. canis on day 14 post-infection period using flow cytometry." (PMID 36006302, 2022). "Both BCG strains elicited Th1-biased antigen-specific polyfunctional effector memory CD4+/CD8+ T cell responses at 10 weeks post-infection, and both vaccines controlled Mtb M2 growth in the lung and spleen." (PMID 36138053, 2022). "We have also determined, to the best of our knowledge for the first time, that a defect in the Env binding to CD4 and the triggered signal led to low fusion, infection and replication capacities, and transmissibility of viruses from these LTNP-EC individuals." (PMID 36140273, 2022). "Females Eut mock-treated showed a significantly high percentage of CD4+ T lymphocytes in the lung compared to females gestated in Eut at day seven after infection with hMPV." (PMID 36159799, 2022). "Strikingly, 4 weeks after infection, the PD-1 expression was already potently induced in both CD4+ and CD8+ T cells in the liver and spleen." (PMID 35666747, 2022). "For instance, dendritic cell-specific ICAM-grabbing nonintegrin (DC-SIGN) on DCs captures HIV-1 particles facilitating transmission and dissemination by trans-infection of CD4-positive (CD4+) T cells (38, –, 40)." (PMID 35297672, 2022).
infection (continued). "CD103+ DC and CD11b+ DC subsets represented the most potent naïve CD4+ T helper cell activators in the infection model of K. pneumoniae." (PMID 36506034, 2022). "In contrast, the CD4 T-cell response increased significantly (p=0.047, two-tailed paired t-test) following second dose in infection-naïve donors." (PMID 35720281, 2022). "This correlation agrees with the central role of T cells, particularly Ct-specific CD4 T cells, in resolution and protection from Ct infection." (PMID 36248887, 2022). "After 24 hours post-infection, primary CD4+ T cells show increased amounts of TCA metabolites aconitate and isocitrate." (PMID 36467738, 2022). "This indicates that infection with the Influenza A virus can promote CD4+ T cell differentiation toward Th1 and Th17 cells, and enhance the body’s pro-inflammatory response." (PMID 35733131, 2022). "Remarkably, mice vaccinated with Bbvac exhibited significant increases in numbers of CD4+ IL-17+ T cells as a response to this brief 7-day infection." (PMID 35196124, 2022). "In contrast, the infection group showed inflammatory lesions, mainly manifested as inflammatory cell infiltration (such as monocytes/macrophages, mDC cells, and CD4+ Tcells, etc.), the disordered arrangement of cell cords, and an unclear structure." (PMID 35639503, 2022). "In the vast majority of patient, the virus population present at the beginning of the infection uses the chemokine receptor CCR5 in addition to CD4 to enter target cells (R5 viruses)." (PMID 35770985, 2022). "But the role of HIFs in the regulation of CD4 T cell responses during infection with M. tuberculosis isn’t well understood." (PMID 36064840, 2022). "Neutrophils are essential for S. aureus clearance, and CD4+ T cells support neutrophil activation by secreting IL-17, which recruits neutrophils to the site of infection, and IFN-γ, which can boost neutrophil effector functions." (PMID 35637249, 2022). "After infection with S. japonicum, WT rats showed a decrease in the percentage of CD4+ T cells in the spleen (P<0.05), LN (P<0.05), and liver (P<0.01), and a slight increase in the percentage of CD8+ T cells in the liver (P<0.05)." (PMID 35584107, 2022). "Treg cells and Th17 cells are subsets of CD4+ T cells, which play an essential role in immune homeostasis and infection." (PMID 36233176, 2022). "As expected, in the context of infection or hybrid immunity, the frequency of spike- plus nucleocapsid-specific CD4 T cells was significantly higher than vaccination alone." (PMID 36584684, 2022). "All mock-depleted mice succumbed to infection by 20 dpi, whereas all CD4/CD8 T cell-depleted mice survived infection." (PMID 36289695, 2022). "In contrast, the proportion of specific effector CD4+ memory T cells was significantly lower and specific effector CD4+ memory T cells were higher after infection than after vaccination." (PMID 35214700, 2022). "It has been shown that in mice Mtb-specific T cells appear in the lungs 1–3 weeks after infection, which is associated with the IFN-γ production by CD4+ T cells and with the control of bacterial burden." (PMID 35163035, 2022). "A representative example was the moderated inverse correlation of S‐specific EM CD4+ T‐cell producing IL‐2 in acute infection compared to the direct correlation found 7 months after infection." (PMID 35415890, 2022). "Single-cycle infection with the reporter virus supports studies of latency establishment in human primary CD4+ T cells by providing accurate quantification of both latent and productive infections." (PMID 35499323, 2022). "We next examined the ratio and frequencies of CD4+ T cells and observed an initial increase in Selplg-/- SMARTA+ CD4+ T cells at 9dpi, which then significantly decreased throughout infection compared to WT T cells." (PMID 35774790, 2022). "At the early time point of day 4 after FV-Katushka-mTagBFP infection, we observed only a trend toward a higher activation rate of CD4+ T cells and CD8+ T cells." (PMID 36527061, 2022).
infection (continued). "The contribution of CD101+ cells within each subset to the overall pool of CD4 T cells was also fully restored to pre-infection levels." (PMID 35867722, 2022). "Dendritic cells and macrophages facilitate the colonization of the virus in lymphoid tissue, further passing the virus to the lymph nodes where initial CD4+ T lymphocytes infection occurs as about 98% CD4+ population resides in lymphoid tissue." (PMID 35956604, 2022). "Infection via all three routes led to robust plasma viremia and depletion of CD4+ T cells over time, thus modeling human pathogenesis." (PMID 34818071, 2022). "Next, we ought to determine the expression of activating and inhibitory ligands on the fraction of CD4+ T cells refractory to ADCC after ex vivo infection." (PMID 35616530, 2022). "More interestingly, studies on HIV-1 transmission have shown DCs participation in CD4+ T cell trans-infection, despite the low infectivity of DCs." (PMID 36313221, 2022). "The lower HIV reservoir and lower activation in CD4+ T cells in adults is attributed to the aggressive CD8+ T cell response in the acute phase of infection, while this phenotype in pediatric ECs is preceded by the tolerogenic environment." (PMID 35911681, 2022). "In line with previous reports, we observed that when CD4+ T cells are stimulated with IL-15, the global levels of infection increase compared to IL-2 treatment." (PMID 35499323, 2022). "To mimic the natural situation, we used two-time points, treatment of 2 μM CD4-PP at the start of infection or 2 h post-infection." (PMID 35821354, 2022). "Careful consideration should be given to patients with HIV infection with CD4 count < 200 cells/mm3, those infected with MDR pathogens, or those with a respiratory source of infection, given these were risk factors for treatment failure." (PMID 36137077, 2022). "Uninfected immunized mice exhibited very low levels of M2e-binding CD4 T cells in the lung and mLN after 2 months, attesting to the great potential of local expansion of these cells following infection." (PMID 35260804, 2022). "On the other hand, our primary cell model represents productive infection of activated CD4 + T cells that are then suppressed by ART." (PMID 35804422, 2022). "For example, although CD4+ T cells are mainly responsible for containing the infection through specific antigen recognition, these T cells are also major contributors to disease at different stages of infection." (PMID 35720353, 2022). "This is consistent with infection experiments that we additionally performed using CD4+ T cells only, where we detected significantly reduced infection using AraC and nonopsonized HIV-1." (PMID 35204813, 2022). "We observed that R5/X4 HIV-GKO total infection (productive and latent), as well as cell viability, were higher in CD4+ T cells stimulated with IL-15 compared to IL-2 stimulated." (PMID 35499323, 2022). "The authors demonstrated that coinfection with T. brucei increased the immune control of chronic Brucella infection and eliminated infection by enhancing CD4+ T cells dependent Th1 immune response." (PMID 36425132, 2022). "The chemokine receptors CXCR4 and CCR5 function as coreceptors for direct infection of CD4+ target cells by HIV." (PMID 36405707, 2022). "If it is assumed that subjects registered without a CD4+ T cell counts (about 50%) are the same as those registered with a CD4+ T cell count, the recent infection would be lower than 20.5%." (PMID 35732657, 2022). "In adaptive cell fractions no significant changes over time were identified in vitro, with the exception of CD4 memory activated fraction, which increases from 24 h onwards post-infection compared to control." (PMID 36271270, 2022). "In contrast, species that are naïve to SIV, such as non-African primates, are unable to resolve the acute phase of infection and instead generate chronic immune activation, CD4+ T cell depletion and eventual immunodeficiency." (PMID 36007015, 2022).